MYCN (MYCN proto-oncogene, bHLH transcription factor)
Diseases named in the same sentence as MYCN in open-access papers (continued):
Sharing a sentence is not in itself a finding about the gene and the disease.
cancer (continued). "We observed that different pathways associated to Th1 are negatively correlated to MYCN in different cancer types." (PMID 33718189, 2021). "In the context of cancer, one recent study showed that in non-MYCN amplified neuroblastoma, low PRMT1 expression was associated with decreased rates of cancer-free survival." (PMID 34688662, 2021). "Since, MYCN overexpression is present in a large group of tumors, we investigated if MYCN was also associated to immune suppression in different MYCN-expressing cancers (SCLC, RMS, RB, Wilms, AML, T-ALL)." (PMID 33718189, 2021). "For example, elevated MYCN leads to increased glycolytic flux and glutaminolysis to promote metabolic reprogramming associated with tumorigenesis in a variety of cancers including neuroblastomas." (PMID 32060267, 2020). "This review explores therapeutic strategies targeting cancer stem-like cells for the treatment of tumors associated with MYCN amplification." (PMID 32547946, 2020). "Across different latent dimensionalities and algorithms, we identified optimal features to stratify sample sex, MYCN amplification, blood cell types, cancer types, and mutation status." (PMID 32393369, 2020). "Among the genetic alterations associated with the development of NB, the most predominant is the amplification of the MYCN oncogene, which is linked to advanced cancer stages, unfavorable biologic features, and a poor prognosis." (PMID 29581853, 2018). "RMS and NB are a major cause of cancer related death in children with a five-year survival rate of around 50% for high-risk NB cases, including those with MYCN amplification, and 40% for PAX3-FOXO1 positive RMS cases." (PMID 29466962, 2018). "MYCN-amplified cases are generally stratified into high-risk subgroup and are treated with multimodal cancer therapy including chemotherapy, surgery, radiotherapy, cis-retinoic acid and immunotherapy." (PMID 29137381, 2017). "This analysis illustrates the potential role of MYCN in NB as a regulator of immune privilege and characterizes the power of in silico analysis for delineating cancer immunology and risk stratification." (PMID 29163537, 2017). "Then, we assessed the sensitivity of these SCLC cell lines to a bromodomain inhibitor, JQ1, since the effects of JQ1 on the reduction of MYC and MYCN expression associated with growth inhibition have been reported in several other types of cancers." (PMID 27764802, 2016). "The MYCN gene encodes N-myc, a helix-loop-helix/leucine zipper transcription factor frequently dysregulated in cancer, that controls the expression of several genes involved in cell cycle progression, cellular invasion, metabolism, and apoptosis." (PMID 26053094, 2015). "New studies have been conducted exploring a functional connection between MYCN and lncRNAs implicated in cancer." (PMID 27077133, 2015). "Our findings suggest that drugging the MYCN network is a promising avenue for the treatment of high risk, neuroblastic cancers." (PMID 25477524, 2015). "Five of these genes, PTEN, TSC2, RPS6KA3, MYCN and Myo5A, form a connected module (module 9) associated with cancer biology." (PMID 24204314, 2013). "As this phenomenon is reminiscent of loss of contact inhibition, a cancer hallmark, we next examined whether CNAs/MYCN overexpression led to further cellular changes that are typical of tumourigenesis." (PMID 38702304, 2024). "This implies that targeting the interaction between DDX3X and MYCN mRNA could potentially hinder the excessive protein synthesis and growth associated with these cancer cells." (PMID 37975412, 2024). "The emerging new knowledge describes previously unspecified direct targets of MYCN oncoprotein that encode for TFs with regulatory capacities, thus facilitating a better understanding of how genomic alterations drive metabolic phenotypes in cancers." (PMID 37835497, 2023).
cancer (continued). "Overall the genomic landscape was stable, with pathogenic or likely pathogenic alterations being identified in 51 cancer genes, with 9 (18%) of them showing alterations being recurrent across different samples (MYCN, CDKN2A/2B, CDK4, GLI1, AKT1, IGF2, MED12, NCOR2)." (PMID 37730754, 2023). "Thus, like MYCN, amplified/overexpressed transcription-related factors—along with some associated components—maintain the cancer genome." (PMID 37514113, 2023). "Here we performed an integrative analysis of public datasets and found that SMAD9 was characterized by specific high expression and dependence among all cancer types and was positively correlated with MYCN expression and a poor prognosis in high-risk NB patients." (PMID 36539767, 2022). "However, later studies showed a strong association of KIT with cancer stem cells, stage 4, and MYCN-amplified tumors, and our data strongly support these findings." (PMID 35887076, 2022). "MYCN amplification and upregulation have been linked to cancer through several mechanisms." (PMID 35883689, 2022). "The clinical course of this cancer may be variable, ranging from aggressive progression to regression, while the amplification of MYCN in this cancer is linked to poor patient prognosis." (PMID 36362869, 2022). "Moreover, apart from MYCN, additional genes that encode for cancer-related TFs, e.g., JUN and TAL2, have been mapped circularized in tumors." (PMID 36139535, 2022). "Since overexpression or amplification of MYC/MYCN and activation of mTOR signaling are often associated with chemoresistance in many cancers including NB, we also wanted to see whether inhibition of these signaling pathways helps to chemosensitize NB cells." (PMID 34565342, 2021). "MYCN is associated with poor prognosis and its over-expression leads to several dysregulations including metabolic reprogramming, mitochondria alteration, and cancer stem cell phenotype." (PMID 33718189, 2021). "The MYCN-Amplified subtype comprises roughly 20% of all NBLs, and 50% of high-risk patients, constituting the most aggressive and least treatable form of this cancer." (PMID 33525507, 2021). "Importantly, the amplification or overexpression of MYCN in the majority of these adult cancers is found to be associated with a poor prognosis." (PMID 33628735, 2020). "Further understanding of the underlying mechanism could reveal a therapeutic target for MYCN-driven cancers." (PMID 33425720, 2020). "Moreover, in the sample from the primary mesonephric-like carcinoma and its liver metastasis a likely pathogenic somatic MYCN mutation (NM_005378.4:c.131C > T, p.(P44L) was found." (PMID 32693840, 2020). "The MYC and related MYCN oncogenes (encoding MYC and N-MYC) are translocated, amplified, or mutated in many cancers, and can dramatically upregulate genes involved in glucose and glutamine metabolism, ribosomal, lipid, and nucleotide biogenesis, and cell cycle progression." (PMID 27500134, 2016). "Interestingly, all let-7 family members contained an identical 2–7nt seed region and the reduced abundance of this seed in malignant GCTs contributed to the subsequent up-regulation of important cancer-associated protein-coding genes, including MYCN." (PMID 25303610, 2015). "The research to date suggests that MYCN not only plays roles in the development and progression of neuronal cancer types, but dysregulated MYCN is also associated with many other types of cancer and may be related to the development and progression of those cancers." (PMID 39802403, 2025). "This relationship may apply more widely than NB and MYCN-driven/implicated cancers." (PMID 39941731, 2025).
cancer (continued). "In summary, 25/663 CpGs can be selected by RFE and used to build the SVM model capable of stratifying NB patients based on MYCN amplification status, wherein these unique CpGs may be useful for building a diagnostic indicator for MYCN amplification in this cancer." (PMID 38249081, 2024). "The FLT3 and MYCN genes are critical in the transcriptional misregulation pathway in cancer, with FLT3 functioning in signal mediation." (PMID 40911615, 2025). "Hyperplastic KCs in PS have some abilities, especially aggressive proliferation, similar to cancer cells accompanied by the high expression of proliferation markers including PCNA or MYCN." (PMID 40768619, 2025). "ARV825 shows significant potential as a therapeutic strategy for combating MYCN-driven cancers and other malignancies." (PMID 39802403, 2025). "Functional investigations revealed that MYCN expression is strictly regulated under physiological conditions, and its expression is required to maintain the properties of stem cells or cancer stem cells." (PMID 39802403, 2025). ",29,176, 177, 178 The intriguing prospect of employing MYCN targeting strategies as a universal approach for managing cancers with MYCN overexpression warrants discussion." (PMID 39802403, 2025). "The ZD55-shMYCN oncolytic adenovirus blocks the cell cycle and induces apoptosis in MNA-NB cells by inhibiting MYCN expression and directly promoting cancer cell lysis." (PMID 41244073, 2025). "Gaining insights into MYCN's biology and its regulation is crucial for the development of targeted therapies and the enhancement of the prognosis for cancer patients displaying MYCN overexpression." (PMID 39802403, 2025). "Future studies should explore the epigenomic effects of N78 to assess its impact on the MYCN genome fully and provide evidence supporting combined cancer therapy." (PMID 40860201, 2025). "Some preclinical studies have demonstrated encouraging results in inhibiting MYCN activity in MYCN-driven cancers." (PMID 39802403, 2025). "Other than MYCN, which is often over‐expressed in poor prognosis disease, there is relatively little information on any cancer‐relevant pathways that distinguish between each prognostic subgroup." (PMID 39021294, 2025). "Numerous studies have indicated that MYCN functions as a key gene influencing ferroptosis and is involved in the initiation and progression of cancer." (PMID 40136455, 2025). "While MYCN overexpression is observed in numerous cancer types, this review aims to consolidate the latest findings regarding MYCN biology." (PMID 39802403, 2025). "Unfortunately, this pediatric cancer type is responsible for 15% of all pediatric oncology deaths, and MYCN stands out as one of the most critical factors in determining prognosis." (PMID 40365336, 2025). "This links the MYCN-driven transcriptional program to increased ribosomal translation, driving the metastatic phenotype in cancer cells." (PMID 40265419, 2025). "NB is one of the most BETi‐sensitive cancers, which was attributed to MYCN amplification, an oncogenic driver found in approximately 20% of high‐risk NB." (PMID 39119816, 2025). "In MB, amplifications of MYCN and MYCL proto-oncogene (MYCL1) have been identified and correlated with cancer aggressiveness and increased risk of metastasis." (PMID 39796780, 2025). "For instance, MYCN-amplified tumors exhibit increased polyamine biosynthesis, which enhances cancer cell proliferation." (PMID 40507292, 2025). "The oncogene MYCN and the cancer-related gene NFE2L2 are located on chromosome 2 at 2p24.3 and 2q31.2, respectively." (PMID 40670349, 2025). "In NB and MB, activating methylation of miRNAs disrupts cell-cycle progression and apoptosis and enhances MYCN proto-oncogene function and increases cancer cell migration." (PMID 39796780, 2025). "Within this cancer, genomic amplification of MYCN serves as a well-established harbinger of poor prognosis, particularly pronounced in the aggressive alveolar subtype." (PMID 39802403, 2025).
cancer (continued). "We analyzed MYCN protein expression in cancer cells to investigate the influence of MYCN status on drug response." (PMID 37975412, 2024). "Our GEMM, which expresses human MYCN in cancer cells, again allowed us to validate these conclusions by an orthogonal RNA ISH assay." (PMID 38898465, 2024). "One of the primary driving forces in reprogramming cancer cell metabolism is the deregulated MYC family proto-oncogenes (MYC, MYCN, and MYCL), which are known to encode master transcriptional factors that regulate metabolic gene expression." (PMID 38488852, 2024). "Our study paves the way for future studies on the mechanistic understanding of how METTL3 can be guided to specific genomic locations by MYCN or other oncogenic transcription factors to drive m6A modification in cancers." (PMID 39528654, 2024). "To reveal the cancer intrinsic network controlled by H2afy, we employed a mouse NB cell line, 9464D, which was originally established from spontaneous tumors of the MYCN-driven transgenic mouse model." (PMID 39255035, 2024). "MYCN blocks differentiation pathways and maintains pluripotency during development and cancer pathogenesis." (PMID 39079981, 2024). "Single-cell RNA sequencing (scRNA-seq) of clinical HGSC samples validated the cancer cell–intrinsic connection between the MYCN gene signature and suppression of IFN type I signaling." (PMID 38748789, 2024). "An analysis of RNA-seq data from 8290 primary tumors representing 21 solid cancer types from TCGA (The Cancer Genome Atlas) revealed that MYCN mRNA expression varied widely within and across cancer types." (PMID 38748789, 2024). "Nevertheless, MYCN remains a very hard-to-drug target due to its pleiotropic roles in both cancer and fetal cerebellar development." (PMID 38689348, 2024). "Drug repurposing provides opportunities for developing drug molecules with new therapeutic indications, especially for MYCN‐amplified NB and RB cancers of high unmet need." (PMID 37975412, 2024). "We also assessed MYCN expression across different cancer cell lines using data from the Cancer Cell Line Encyclopedia (CCLE)." (PMID 38748789, 2024). "Our study indicates the feasibility of ceftriaxone repurposing and reveals previously unrecognized drug targets, which merit rational drug design for MYCN‐amplified tumors and future studies of these cancers." (PMID 37975412, 2024). "We then extended our study to a panel of human cancer cell lines exhibiting differential MYC/MYCN levels." (PMID 38493213, 2024). "We focused on MYCN interactors with histone modifying enzymatic activity or those considered promising targets for anti-cancer therapies." (PMID 38547242, 2024). "The molecular pathogenesis of this pediatric cancer involves complex genetic alterations, such as MYCN amplification, chromosomal abnormalities, and gene expression changes." (PMID 39612452, 2024). "The transcription factor and proto-oncogene MYCN is reviewed as a potential specific target for cancer therapy." (PMID 39867575, 2024). "Cathepsin B, implicated in both tumor invasion and metastasis across various cancers, is notably overexpressed in cancers with MYCN gene amplification." (PMID 39981299, 2024). "Enhanced and deregulated expression of MYCN, often resulting from gene amplification, drives the development of multiple cancers, including tumors of the nervous system, both in children and adults." (PMID 37407554, 2023). "We have identified a protein called PA2G4, which is a cofactor for MYCN in promoting cancer cell growth." (PMID 36980710, 2023). "Recent, pre-clinical evidence indicates the feasibility of direct and indirect targeting of IGF2BP1 and MYCN in cancer treatment." (PMID 37246217, 2023). "Inhibition of MYCN protein binding partners can markedly reduce MYCN stability and is an emerging treatment strategy for MYCN-driven cancers." (PMID 36980710, 2023).
cancer (continued). "Amplification of MYCN results in cancer malignancies such as cell cycle arrest in G1 phase and morphological differentiation, so targeting MYCN is a promising therapy." (PMID 37745860, 2023). "Among them, the amplification and high expression of the MYCN gene are often positively correlated with the malignant progression and poor prognosis of various malignant tumors such as NB, receiving widespread concern." (PMID 36770809, 2023). "The MYCN silencing caused by BGA002 constitutes an innovative precision medicine approach, enabling the inhibition of mTOR to occur only in cancer cells, and leaving normal cells unaffected." (PMID 36765949, 2023). "While targeting c-MYC and/or MYCN for cancer treatment is a major challenge, these proteins represent a potential group of targets for which drugs are already available or are in development." (PMID 37760568, 2023). "Taken together, considering the metastatic role of MYCN, it is an ideal and the most wanted target for cancer therapy." (PMID 37274289, 2023). "As a proto-oncogene, MYCN is frequently deregulated in human cancers, and MYC-dependent metabolic reprogramming is critical for tumorigenesis." (PMID 37190157, 2023). "Nevertheless, our pan-cancer analysis showed that MYCN appears to be a protective factor for ccRCC and is much less expressed in renal tumor tissues." (PMID 37213288, 2023). "The deregulated activity of both c-MYC and MYCN has also been shown to play a critical role in maintaining a stem-like state in cancer cells by blocking differentiation pathways and promoting the expression of self-renewal and pluripotency genes." (PMID 37760568, 2023). "MYCN has a highly restricted pattern of expression in normal cells and is an ideal target for cancer therapy but is undruggable by traditional approaches." (PMID 36765949, 2023). "Next, we prioritized those MYCN interactors that are involved in histone modifications and those considered promising targets for anti-cancer therapies." (PMID 37781575, 2023). "Previous studies have shown that MYCN amplification is the main poor prognostic marker of NB, which generally indicates cancer cell metastasis." (PMID 37156775, 2023). "The results of this study showed that compared with normal tissues, the expression of CDKN2A and ZBP1 in cancer cells was significantly increased, while the expression of MYCN was on the contrary." (PMID 37878133, 2023). "Modeling of the pediatric cancer in diverse animal models is necessary to understand the role of MYCN in metastasis." (PMID 37274289, 2023). "Molecular processes central to the MYCN’s oncogenic activity include the hallmarks of cancer influencing the cell cycle, apoptosis or cell death and cellular metabolism reviewed elsewhere." (PMID 37274289, 2023). "Our study adds to the increasing evidence that the multi-modal metabolic targeting of cancer is a promising adjuvant therapy to tackle MYCN-amplified NB." (PMID 37623854, 2023). "Currently, targeting MYCN through inhibiting bromodomain-containing proteins and Aurora Kinase A in various cancers is well studied." (PMID 37543638, 2023). "This occurred by induction of a pro-apoptotic phenotype, suggesting MYCN and mitotic dysregulation primes cells for apoptosis but cancer-specific cell alterations allow survival, as has been demonstrated previously." (PMID 37958555, 2023). "The BRD4 inhibitor (JQ1) competes with BRD4 for binding to acetylated lysines, displacing BRD4 from super-enhancers within the MYC oncogene and reducing MYC expression, resulting in anti-cancer effects in hematopoietic cancers, PDAC and MYCN-driven cancers." (PMID 37755397, 2023). "NCYM stabilizes MYCN and β-catenin via direct binding and inhibition of GSK3β and promotes cancer progression in various tumors." (PMID 38074684, 2023). "MYCN expression is manly restricted to cancer cells (and expecially in MNA-NB cells where it is highly expressed), while it has a very limited pattern of expression in normal cells." (PMID 35490242, 2022).